HHLA2 (HHLA2 member of B7 family)
Diseases named in the same sentence as HHLA2 in open-access papers (continued):
Sharing a sentence is not in itself a finding about the gene and the disease.
tumor (continued). "Therefore, HHLA2 may serve as a new therapeutic target for tumour immune checkpoints in addition to CTLA-4, PD-1, and PD-L1." (PMID 33962626, 2021). "In addition, knockdown of HHLA2 inhibited tumor growth in vivo." (PMID 34152094, 2021). "Furthermore, the positive impact of HHLA2 in KIRC may be explained by a compensatory up-regulation of this molecule in tumor microenvironment, which fights the tumor via an activated immune response." (PMID 32509772, 2020). "Along with previous findings, in ICC, HHLA2 may not only work as an inhibitory checkpoint, but also potentially contribute to tumor progression through binding to TMIGD2, a recently identified ligand which is also involved in angiogenesis, or through other unknown mechanisms." (PMID 30885276, 2019). "HHLA2 overexpression was associated with sparser CD3+ tumor infiltrating lymphocytes (TILs), CD8+ TILs and a higher CD4 + Foxp3+/CD8+ TIL ratio, whereas PD-L1 expression was associated with prominent T cells and CD163+ tumor associated macrophages infiltrations." (PMID 30885276, 2019). "Consequently, expression of HHLA2 in blood specimens may reflect the systemic immune status relating to circulating tumor cells and antigen presenting cells (APCs)." (PMID 29774123, 2018). "This study identifies HHLA2 as a key regulator of c-Met signaling in HCC, promoting tumor progression and angiogenesis." (PMID 40394703, 2025). "The low-risk group exhibited significantly elevated expression levels of HHLA2, NRP1, and TNFSF15, suggesting a less immunosuppressive tumor microenvironment." (PMID 40243888, 2025). "Collectively, our findings demonstrate that HHLA2 promotes HCC cell proliferation, migration, and invasion in vitro, and enhances tumor growth and angiogenesis in vivo." (PMID 40394703, 2025). "HHLA2 was also established as an independent prognostic factor for disease-free survival in MTC patients, underscoring its impact on tumor immunity and progression." (PMID 40255615, 2025). "This strategy offers the advantage of directing HHLA2 CAR-T cells to the tumor site, thereby enhancing their anti-tumor efficacy." (PMID 40255615, 2025). "On the other hand, the binding of HHLA2 and KIR3DL3 leads to the inhibition of T cells and mediates tumor resistance against NK cells." (PMID 38786018, 2024). "This study seeks to investigate the clinical significance of CCR4, CCL17, CD73, and HHLA2 in HCC, exploring their interconnectedness within the tumor immune microenvironment." (PMID 38914802, 2024). "In one prior study investigating a tumor marker and TILs in MTC, the authors suggested that this tumor marker (HHLA2) and TILs are closely related, which together affect the prognosis and survival of MTC." (PMID 38903715, 2024). "NLRP1 is also significantly associated with most immune‐stimulating genes except for CD276, HHLA2, NTSE, PVR, TNFSF18 and UNBP1 in the HNSC‐excluded tumours." (PMID 39318060, 2024). "The multivariate Cox proportional regression model identified significant predictors as independent prognostic factors for OS: CCL17-T high, CD34 high, CCR4 + CD73 + ≥ 13, CCR4-T high, CD73-T high, HHLA2, MVI, Treg/CD8 ≥ 1, and tumor size ≥ 5 cm." (PMID 38914802, 2024). "In our research, the level of HHLA2 expression correlated positively with TILS (T cells, B cells, natural killer (NK) or dendritic cells (DC) infiltrating the tumor, the primary response of the host immune system) (p = 0.019)." (PMID 36982953, 2023). "In the tumour microenvironment, IGPR-1 expressed on the cell surface of endothelia binds HHLA2, expressed not only on the tumour cells but also on tumour-associated macrophages." (PMID 34982945, 2022). "Related to the proliferation and function of immune cells or tumor progression, T cell proliferation-related genes (TRGs) involve hundreds of protein-coding genes which include CTLA4, HHLA2, PRKCQ, IL4I1, IL20RB, HOMER1, DHPS, and so on." (PMID 36118894, 2022).
tumor (continued). "HHLA2/PD-L1 co-expression was significantly correlated with a high density of CD8 + and CD4 + tumor-infiltrating lymphocyte (TIL)." (PMID 36118894, 2022). "The relationships between HHLA2 expression and clinicopathological features, prognosis, and CD8+ tumour-infiltrating lymphocytes (TILs) in patients were analysed." (PMID 33962626, 2021). "The average QIF scores of PD-L1, HHLA2, B7H3, IDO-1 and Galectin-9 were significantly higher in the stromal compartment than in the tumor subregion." (PMID 35145510, 2021). "In our study, the expression levels of HHLA2 and TMIGD2 in different OSCC pathology grades, tumor sizes, and lymph node status were analyzed by the one-way analysis of variance method and t-test method." (PMID 31089395, 2019). "Our findings in the HDTVi HCC mouse model suggest that HHLA2’s primary oncogenic contribution is through direct tumor promotion rather than generalized immune suppression." (PMID 40394703, 2025). "On the other hand, a study on MTC revealed that HHLA2 expression was confined to tumor tissues and absent in adjacent noncancerous tissues." (PMID 40255615, 2025). "Co-injection either wild-type (WT) or kinase-dead (KD) c-Met, along with HHLA2 or control vector, demonstrated HHLA2 enhanced tumor growth in WT c-Met mice but not in KD c-Met mice." (PMID 40394703, 2025). "Notably, there was an inverse relationship between HHLA2 expression and CD8+ tumor-infiltrating lymphocytes, indicating a possible role in immune evasion." (PMID 40255615, 2025). "HHLA2 acts as an oncogene in HCC by activating c-Met, promoting tumor progression and metastasis." (PMID 40394703, 2025). "Moreover, in the tumor tissue obtained from patients with CRC, high HHLA2 levels corresponded to the advanced T and N stages, and more prominent distant recurrence in the study performed on 134 CRC cases." (PMID 38786018, 2024). "The mechanism allowing for tumor cells to maintain HHLA2 expression does not depend on cytokines, hypoxia, lactic acidosis, glucose-deprived environments, or demethylation." (PMID 38786018, 2024). "In the validation cohort, tumor number, size, age, differentiation, MVI, GGT, CD34, CD66b, Treg/CD8, CCR4-T, CCL17-T, CCL17-I, HHLA-2, CD73-T, and CCR4 + CD73 + cells have been proved to be prognostic variables for both OS and RFS in univariate analysis (all P < 0.050)." (PMID 38914802, 2024). "Only 44.4% of patients with no metastases exhibited HHLA2 expression in the tumor tissue in comparison with 83% of patients with metastases, and patients with stage IV of the disease exhibited the highest percentage of HHLA2-positive cases." (PMID 38786018, 2024). "Interestingly, there was a marked decrease in tumor-infiltrating CD4+ and CD8+ T cells in PNETs with high HHLA2 and B7x expression." (PMID 38786018, 2024). "High HHLA2 expression was detected in CRC tumor tissues compared to the adjacent noncancerous tissues." (PMID 36982953, 2023). "Despite HHLA2 expression on many ccRCC in situ, A498 and 786-O ccRCC tumor cell lines do not express HHLA2 in vitro." (PMID 37891555, 2023). "A498 and 786-O ccRCC tumor cell lines do not express HHLA2 in vitro, but HHLA2 expression was observed when grown as subcutaneous xenografts in NSG immunodeficient mice." (PMID 37891555, 2023). "Induction experiments using various cytokines and culture conditions failed to induce HHLA2 expression in A498 and 786-O tumor cell lines in vitro." (PMID 37891555, 2023). "Our findings suggest that t-HHLA2 and s-HHLA2 may produce different effects on the progression of UTUC, warranting further research on the effects of the stromal cells in the tumor environment." (PMID 36598731, 2023). "HHLA2 and its inhibitory receptor, KIR3DL3, are targets for tumor immunotherapy." (PMID 37891555, 2023). "The expression of HHLA2 was then examined in 15 pairs of HCC and non-tumor tissues." (PMID 35371079, 2022).
tumor (continued). "However, 24, 6, 12, 21 and 6 patients displayed higher HHLA2, B7H3, IDO-1, PD-L1 and galectin-9 expression in the tumor subregion, respectively." (PMID 35145510, 2021). "Unfortunately, no data on the regulation of HHLA2 expression in tumour cells by immunological mechanisms are as yet available." (PMID 32071413, 2020). "Moreover, HHLA2 was positively correlated with immune-related genes, while HHLA2 and CD8 expression exhibited a consistent trend in KIRC tumor samples." (PMID 32509772, 2020). "Immunohistochemical analysis demonstrated that HHLA2 was mainly expressed in the membrane and/or cytoplasm of normal epithelial cells and tumor cells." (PMID 29774123, 2018). "HHLA2 expression showed a significant negative correlation with the depth of tumor invasion, distant metastasis, and tumor-node-metastasis (TNM) stage (P = 0.0331, P < 0.0001, and P = 0.0032, respectively)." (PMID 29774123, 2018). "Our detection of HHLA2 in the serum of HCC patients with high tumor HHLA2 expression underscores its potential as a non-invasive liquid biopsy marker for disease monitoring and identifying patients most likely to benefit from c-Met inhibitor therapy, offering a novel approach to precision medicine." (PMID 40394703, 2025). "Notably, serum HHLA2 levels correlated positively with tumor HHLA2 levels, suggesting its potential as a non-invasive biomarker, although more sensitive detection methods are needed." (PMID 40394703, 2025). "Patients with higher HHLA2 expression exhibited poorer anti-tumor immunological responses, suggesting that despite more abundant immune infiltrations, immune cells might be deprived of their functions in HCC with elevated HHLA2 expression." (PMID 38786018, 2024). "Moreover, only IL-10 and BMP4 show modest enhancement of HHLA2 expression in monocytes and dendritic cells, but not in ccRCC tumor cells." (PMID 37891555, 2023). "There was a negative correlation between HHLA2, anti-tumor cytokines and pro-tumor growth factors." (PMID 36982953, 2023). "However, the biological functions and regulatory roles of one of its members, HHLA2, in the tumor immune microenvironment have not been explored." (PMID 35371079, 2022). "In addition, tumoral HHLA2 expression and stromal levels of PD-L1, B7H3 and Galectin-9 could predict tumor features, the immune response in the microenvironment and patient outcomes." (PMID 35145510, 2021). "It has been shown that HHLA2 could play an immunosuppressive role in the tumor microenvironment and that the expression of negative immune checkpoint molecules is always correlated with poor prognosis." (PMID 31089395, 2019). "Previous studies have reported that it was widely expressed in patients with PD-1-negative NSCLC, which suggests HHLA2 might be promising immunotherapy target for tumor patients who do not response to PD-1 related therapy." (PMID 31379814, 2019). "Therefore, in the future, more rigorous researches and meta-analysis with high-qualified evidence are needed to determine the prognostic value of HHLA2, especially in KIRC, and whether it is correlated with tumor types." (PMID 31379814, 2019). "Although HHLA2 and FAP are expected to be associated with anti-tumor immune response, we could not verify whether the expression of HHLA2 and FAP affects the efficacy of immune checkpoint inhibitors, because only a few cases used immune checkpoint inhibitors in this study." (PMID 36598731, 2023). "However, studies of the tumour-intrinsic effect of HHLA2 signalling have not been reported." (PMID 33962626, 2021). "Moreover, neither HHLA2 expression nor TMIGD2 expression was related to tumor size." (PMID 31089395, 2019). "Neither HHLA2 nor TMIGD2 expression levels were significantly correlated with pathology grade, tumor size, or lymph node status." (PMID 38786018, 2024).
tumor (continued). "A498 and 786-O ccRCC tumor cell lines were tested with an extensive set of candidate cytokines, including a combination of IL-10 and IFN-γ; however, none induced HHLA2 expression in these cell lines." (PMID 37891555, 2023). "Interestingly, overexpression of HHLA2 in the METTL3-depleted model could significantly reverse and promote the tumor growth of 786-O cells (P < 0.0001), suggesting that HHLA2 overexpression could reverse the inhibition of tumor growth induced by METTL3 depletion." (PMID 35794583, 2022). "Tumours with high HHLA2 expression levels contained slightly, but significantly, more tumour-infiltrating CD8+ cells compared to tumours without HHLA2 expression." (PMID 32071413, 2020). "As tumor-infiltrating immune cells are activated cells, the crosstalk between TMIGD2 and HHLA2 is unlikely to explain the inhibition of the antitumor immune response, and new receptor(s) for HHLA2 need to be identified in the future." (PMID 32477326, 2020). "Furthermore, this study did not explore whether HHLA2 and FAP jointly or separately increase or decrease the anti-tumor immune response or the mechanism involved, and this should be investigated further." (PMID 36598731, 2023).
infection (2 papers, 2019). The state of being infected such as from the introduction of a foreign agent such as serum, vaccine, antigenic substance or organism. "These include the tumor suppressor gene, RASEF (expressed only during the line 61 host response) and a gene involved in regulating cell-mediated immunity, HHLA2 (highly expressed in line 72 following infection)." (PMID 30678299, 2019). "In order to further investigate the biological function of HHLA2 in human ccRCC cell lines, we establish the stable knockdown expression of HHLA2 in ccRCC cell lines 786-O and ACHN by using shRNA via lentiviral infection and cell sorting by using detecting GFP expression in the flow sorter." (PMID 31015801, 2019).
gastrointestinal tumors (1 paper, 2025). "Compared to immune checkpoint blockade therapy, more research has focused on HHLA2 as a prognostic biomarker for gastrointestinal tumors." (PMID 40909948, 2025).
hematological cancers (1 paper, 2021). "In addition to HLA class I ligands, the HERV-H LTR-associating 2 (HHLA2) molecule, a member of the B7 family that is highly expressed in several solid and hematological cancers, was recently identified as a ligand for KIR3DL3." (PMID 34359667, 2021).
HHLA2 also shares sentences with these, for which no sentence is quoted: esophageal cancer (3 papers); non-small cell lung carcinoma (3); adenocarcinoma (2); cholangiocarcinoma (2); gastric tumor (2); oral cancer (2); papillary thyroid carcinoma (2); acute myeloid leukaemia (1); Autoimmunity (1); B-cell acute lymphoblastic leukaemia (1); B-cell non-Hodgkin lymphoma (1); bladder cancer (1); chronic obstructive pulmonary disease (1); endocrine tumors (1); gastrointestinal neuroendocrine tumors (1); Hodgkins lymphoma (1); IgA nephropathy (1); lactic acidosis (1); lymphoma (1); malignant pleural mesothelioma (1); neuroendocrine tumors (1); pancreas neoplasms (1); pancreatic neuroendocrine tumor (1); peripheral T-cell lymphoma (1); rectum cancer (1); T-cell acute lymphoblastic leukaemia (1); T-cell lymphoma (1); thyroid tumor (1); viral diseases (1).